PTN (pleiotrophin)
Diseases named in the same sentence as PTN in open-access papers (continued):
Sharing a sentence is not in itself a finding about the gene and the disease.
systemic lupus erythematosus (4 papers, 2015 to 2023). An autoimmune multi-organ disease typically associated with vasculopathy and autoantibody production. "It has also been described for HERV-E.FABP7 in leukemic B cells; HERV-E.PTN, HERV-E.EDNRB, and HERV-E.MID1 in placenta but not in blood cells; and HERV-E clone 4-1 in peripheral blood lymphocytes (CD4+, CD8+ and B cells) but not in neutrophils from patients with systemic lupus erythematosus (SLE)." (PMID 25785516, 2015).
brain injury (3 papers, 2022 to 2025). Acute and chronic (see also brain INJURIES, CHRONIC) injuries to the brain, including the cerebral hemispheres, CEREBELLUM, and brain STEM. "It suggests that PTN plays a vital pathophysiological role in recovering from ischemic brain injury." (PMID 39829367, 2025). "Hereby, this review describes the roles and related regulatory pathways of PTN in brain injuries, to find its potential value in the treatment of brain injuries." (PMID 39829367, 2025). "Considering this, this review focuses on the roles and related regulatory pathways of PTN in brain injuries, what is known to date." (PMID 39829367, 2025). "The role of PTN in these mechanisms is supported by independent investigations that proposed that PTN signaling mediates neovascular formation after acute ischemic brain injury." (PMID 35967328, 2022). "It suggests PTN as a promising candidate for advancing the treatment of brain injuries clinically." (PMID 39829367, 2025). "Meanwhile, PTN actively exerts neuroprotective effects and participates in the repairment of brain injuries, including hypoxic-ischemic brain injury, preterm white matter injury, traumatic brain injury, and neurodegenerative diseases." (PMID 39829367, 2025). "Furthermore, PTN is reported to participate in the development of brain and play a neuroprotection in brain injuries." (PMID 39829367, 2025). "However, no reviews comprehensively summarize the roles of PTN in brain injuries." (PMID 39829367, 2025). "However, there have no reviews been published about the roles of PTN in brain injuries." (PMID 39829367, 2025).
diabetes (3 papers, 2023 to 2025). "Additionally, CXCL13, CA6, SDC1, and PTN demonstrated mediating effects in the association between Health Behaviors and outcomes such as diabetes, renal disease, and death." (PMID 41290610, 2025). "CXCL13, CA6, SDC1, and PTN, on the other hand, mediate the relationship between Health Behaviors and renal diseases, diabetes, and death." (PMID 41290610, 2025).
Hepatic steatosis (3 papers, 2017 to 2025). Steatosis is a term used to denote lipid accumulation within hepatocytes. "Interestingly, in a knock-out mouse model, PTN deletion was found to induce browning of periovarian adipose tissue and protect against diet-induced hepatic steatosis." (PMID 41303424, 2025). "PTN may thus represent a new potential therapeutic target for the prevention of hepatic steatosis and further progression to HCC after chronic HBV infection." (PMID 28557334, 2017).
lung adenocarcinoma (3 papers, 2012 to 2025). A carcinoma that arises from the lung and is characterized by the presence of malignant glandular epithelial cells. "For example, targeting the menin-PRC2 complex (which includes EZH2) suppresses lung adenocarcinoma growth by mediating H3K27me3-dependent silencing of the oncogenic growth factor pleiotrophin (PTN)." (PMID 40599544, 2025). "Menin inhibits lung adenocarcinoma proliferation, migration, and tumor growth in mice in part by suppressing the expression of the growth factor pleiotrophin (PTN), similar to its effect in pNETs." (PMID 39336822, 2024). "Similar to its effect in lung adenocarcinoma, menin inhibits melanomagenesis by inhibiting the expression of the growth factor PTN and its cell surface receptor RPTPβ/ζ." (PMID 39336822, 2024).
meningioma (3 papers, 2017 to 2023). A generally slow growing tumor attached to the dura mater. "Furthermore, the genes CLU and PTN, which are known to be highly expressed in other neoplastic cells, were also found to be commonly expressed in meningioma neoplastic cells." (PMID 37880655, 2023). "NME1, NFE2, SFN, PTN, CALN1, GABRA5 and several components involved in neural differentiation and receptors associated with neural transmitter were also found to illicit an autoimmune response in the meningioma patients indicating that there could be some alterations in these components." (PMID 28938569, 2017). "In contrast, PTN expression in meningioma cells decreased over time in 3D monoculture conditions, perhaps explaining the loss of PTPRZ1 expression from meningioma cells in the absence of a tumor microenvironment." (PMID 32968068, 2020).
schizophrenia (3 papers, 2013 to 2024). A major psychotic disorder characterized by abnormalities in the perception or expression of reality. "A micro-array study of biopsies from olfactory epithelium from patients with schizophrenia, bipolar disorder, and healthy volunteers found a more than 50% reduction in the expression of pleiotrophin, a growth factor which enables β-catenin release from the plasma membrane, in schizophrenia." (PMID 24403877, 2013). "Besides, the depletion of BRN2 and PTN can lead to schizophrenia through different mechanisms." (PMID 39334490, 2024).
Anxiety (2 papers, 2014 to 2018). Intense feelings of nervousness, tension, or panic often arise in response to interpersonal stresses. "Disruption of either PTN or the homologous protein midkine has been associated with heightened anxiety in mice." (PMID 25000129, 2014). "PTN KOs exhibited cognitive rigidity, heightened anxiety, behavioral reticence in novel contexts and novel social interactions suggestive of neophobia, and lamina-specific decreases in neuronal area and increases in neuronal density in the lateral EC." (PMID 25000129, 2014). "In mouse models, pleiotrophin regulates synaptic plasticity, spatial learning, and anxiety-like behaviors, at least in part through enhancement of GABAergic transmission, supporting a proposed role for the pleiotrophin-Nrx interaction in regulating synaptic function." (PMID 30100184, 2018). "Abnormal neuronal size and packing density in the lateral EC of PTN KOs might therefore contribute to their heightened anxiety and neophobia." (PMID 25000129, 2014). "The purpose of the current study was to more fully characterize the neurobehavioral and neuroanatomical phenotype of PTN KOs, with emphasis on the domains of learning and memory, cognitive-behavioral flexibility, exploratory behavior and anxiety, and social behavior." (PMID 25000129, 2014).
brain glioma (2 papers, 2018 to 2024). A malignant glioma that involves the brain. "The purpose of the present study was to explore clinical roles of CREB3L1 and PTN expression in brain glioma progression." (PMID 29531016, 2018). "Our results indicate that the CREB3L1 and PTN expression are useful indicators that help to identify the nature of the glial cells and malignant degrees of brain gliomas." (PMID 29531016, 2018). "The present study was conducted to investigate the clinical significance of cAMP responsive element binding protein 3 like 1 (CREB3L1) and pleiotrophin (PTN) expression in prognosis of patients with brain gliomas." (PMID 29531016, 2018). "In conclusion, the present study indicates that the CREB3L1 and PTN expressions provide a clinical cue in helping to realize grade of brain glioma cells." (PMID 29531016, 2018). "Our study could provide an important clue to the clinical roles of CREB3L1 and PTN expressions in evaluating grade-versions of brain gliomas, and thus may offer an appropriately therapeutic option for the cancer patients." (PMID 29531016, 2018). "Interestingly, in brain glioma the expression of CREB3L1 negatively correlates with PTN levels, absence of CREB3L1 accompanied by the presence of PTN implied a short survival time and poor prognosis for brain glioma patients." (PMID 38164349, 2024).
breast tumors (2 papers, 2010 to 2023). "We also found that PTN is expressed by cancer cells in human breast tumors." (PMID 36828390, 2023).
cardiac ischemia (2 papers, 2024). "Compared with LTBP2 and OGN, PTN exhibited enrichment in myocardial infarction, which is the primary cause of cardiac ischemia and subsequent heart failure." (PMID 39722892, 2024).
chorioamnionitis (2 papers, 2016 to 2023). A morphologic finding indicating inflammation of the fetal sac membranes. "Both AF MDK and PTN concentrations were lower in pregnancies complicated by chorioamnionitis than in healthy pregnancies." (PMID 27089523, 2016). "In the amniotic fluid of chorioamnionitis, the expression level of PTN is low, suggesting that the abnormality of PTN may serve as a marker for intrauterine infection." (PMID 37627278, 2023). "Both MDK and PTN concentrations were found to be lower in pregnancies that were complicated by chorioamnionitis at term, raising the possibility that these growth factors might be useful as markers for infection." (PMID 27089523, 2016). "Both MDK and PTN levels were found to be lower in pregnancies complicated by chorioamnionitis, suggesting that these growth factors might be used clinically as markers for infection." (PMID 27089523, 2016). "Interestingly, both MDK and PTN concentrations were lower in term samples from pregnancies complicated by chorioamnionitis than in those from healthy pregnancies, suggesting that infection either decreases the expression or accelerates the degradation of these growth factors." (PMID 27089523, 2016).
Cirrhosis (2 papers, 2017 to 2023). A chronic disorder of the liver in which liver tissue becomes scarred and is partially replaced by regenerative nodules and fibrotic tissue resulting in loss of liver function. "As hallmark features of TME in HCC, we postulated that PTN may mediate the role of CAF in cirrhosis-HCC progression." (PMID 37259127, 2023). "Thirdly, the role of PTN in mediating CAF in cirrhosis-HCC progression need further exploration.Data has shown that CAFs regulate many wide-range of genes and transcription factors to activate signals which trigger fibroblasts to promote carcinogenesis." (PMID 37259127, 2023). "The median serum PTN level in the 17 patients with HBV‐related cirrhosis was 1294.20 pg/ml (mean = 1294.20 ± 180.57 pg/ml)." (PMID 28557334, 2017). "Clinical analysis also revealed that PTN was associated with liver cirrhosis and HCC, which further indicated that PTN may be an important target of cirrhosis and HCC induced by HBV." (PMID 37259127, 2023). "Since HBV infection is an important cause of HCC and liver fibrosis/cirrhosis is the key intermediate link of HBV-HCC, we explored whether PTN can mediate the role of CAF in cirrhosis-HCC progression." (PMID 37259127, 2023). "The serum PTN level was highest in patients with HBV‐related cirrhosis." (PMID 28557334, 2017). "The results showed that PTN was highly expressed in cirrhosis compared with NAFLD and HCC, suggesting its role in initiating liver fibrosis/cirrhosis." (PMID 37259127, 2023). "In this study, we uncovered PTN to be an important mediator of HBV cirrhosis-HCC progression through integrated bioinformatics analysis and validated its clinical significance in cirrhosis-HCC progression patients." (PMID 37259127, 2023). "The statistical analysis showed that increased expression of PTN was correlated with HBV infection, cirrhosis, adjacent organ invasion, microscopic vascular invasion and advanced TNM stage." (PMID 28557334, 2017). "We measured serum PTN levels in 15 healthy volunteers, 25 patients with HBV‐related hepatitis, 17 patients with HBV‐related cirrhosis, 20 patients with HBV‐related HCC and 11 patients with non‐HBV‐related HCC." (PMID 28557334, 2017). "Statistical analysis showed that increased expression of PTN was correlated with HBV infection, cirrhosis, adjacent organ invasion, microscopic vascular invasion and advanced TNM stage (P < 0.05)." (PMID 28557334, 2017). "The PTN found in this study may be a CAF specific biomarker and an important molecular mediator mediating HBV infection-related liver fibrosis/ cirrhosis and HCC." (PMID 37259127, 2023). "Bioinformatics and vitro experiments confirm PTN was upregulated in HCC and promoted the proliferation of tumor cells, and HBV infection could initiate PTN to perform cirrhosis-HCC progression." (PMID 37259127, 2023). "Hence, we compared the PTN expression level among NAFLD, cirrhosis, and HCC." (PMID 37259127, 2023).
dilated cardiomyopathy (2 papers, 2020 to 2022). Cardiomyopathy which is characterized by dilation and contractile dysfunction of the left and right ventricles. "PTN may be a novel potential diagnostic and therapeutic target for dilated cardiomyopathy." (PMID 36082132, 2022). "Abnormal expressions of DES and PTN were also reported in dilated cardiomyopathy (DCM)." (PMID 32423033, 2020).
gastric cancer (2 papers, 2017). A primary or metastatic malignant neoplasm involving the stomach. "For example, in gastric cancer, PTN overexpression was identified as an independent predictor of lower recurrence-free and overall survival." (PMID 28969035, 2017).
heart failure (2 papers, 2024 to 2026). Inability of the heart to pump blood at an adequate rate to meet tissue metabolic requirements. "Notably, in heart failure, the PTN-PTPRZ1 axis mediated specific crosstalk between cardiac fibroblasts and N4-ALK neurons." (PMID 41860822, 2026). "Based on these findings, we propose that PTN could be synthesized during heart failure to regulate collagen secretion, leading to overall extracellular matrix deposition." (PMID 39722892, 2024).
liver cancer (2 papers, 2020 to 2023). An epithelial or non-epithelial malignant neoplasm that arises from the liver. "Another study found that miR-384 was downregulated in HBV-related HCC tissue and promoted liver cancer cell proliferation and metastasis by targeting the oncogene pleiotrophin." (PMID 32128112, 2020). "miR-384 downregulates the oncogene pleiotrophin (PTN) in liver cancer cells by directly binding to 3′-UTR, whereas PTN, an oncogene, acts on liver cancer cells and promotes cell proliferation and adipogenesis through the function of the N-syndecan growth factor." (PMID 36969840, 2023).
liver cirrhosis (2 papers, 2017 to 2023). "The results further suggest that PTN plays an important role in the evolutionary processes from hepatitis, liver cirrhosis to HCC caused by HBV, particularly the transition from liver cirrhosis to HCC." (PMID 28557334, 2017). "Our results suggest that PTN plays an important role in the evolutionary processes from hepatitis, liver cirrhosis to HCC caused by HBV, particularly in the transition from liver cirrhosis to HCC." (PMID 28557334, 2017). "Additionally, the expression level of PTN showed an increasing trend in liver cirrhosis samples with disease stage (F0-F4)." (PMID 37259127, 2023).
lymphoma (2 papers, 2022). A malignant (clonal) proliferation of B- lymphocytes or T- lymphocytes which involves the lymph nodes, bone marrow and/or extranodal sites. "Tumor-related macrophages increase the proportion of tumor stem cells in lymphoma via the secretion of PTN." (PMID 35281077, 2022). "PTN induces the generation of lymphoma stem cells via the β-catenin pathway." (PMID 35740975, 2022). "PTN is also a soluble protein molecule secreted by TAMs, which is significantly positively correlated with the expression of PTPRZ1 (PTN receptor) in lymphoma." (PMID 35740975, 2022).
myocardial infarction (2 papers, 2022 to 2024). Gross necrosis of the myocardium, as a result of interruption of the blood supply to the area, as in coronary thrombosis. "According to previous studies, Pleiotrophin, a pro-angiogenic factor, was significantly expressed in rat models of myocardial infarction and DCM patients." (PMID 36056063, 2022).
non-small and small cell lung cancer (2 papers, 2002 to 2018). "High PTN level is positively related to the stage of disease in non-small and small cell lung cancer and inversely to the reaction to treatment." (PMID 30427932, 2018). "Of the 63 small cell lung cancer patients in the study pleiotrophin serum levels were elevated in 55 cases (87%) and in 14 cases (63%) of the 22 non-small cell lung cancer patients." (PMID 11953815, 2002).
osteoarthritis (2 papers, 2022 to 2023). A noninflammatory degenerative joint disease occurring chiefly in older persons, characterized by degeneration of the articular cartilage, hypertrophy of bone at the margins and changes in the synovial membrane. "The cellular communication among chondrocyte subtypes mediated by signaling pathways, such as PTN, VISFATIN, SPP1, and TGF-β, was selectively altered in Osteoarthritis." (PMID 37082621, 2023).
Senile plaques (2 papers, 2024). Senile plaques are extracellular deposits of amyloid in the gray matter of the brain. "miR-137 modulates neuroinflammation by antagonizing the expression of Pleiotrophin (PTN), a proinflammatory neurotrophic factor that is enriched in senile plaques in AD brains." (PMID 39000336, 2024).
steatosis (2 papers, 2017 to 2021). Increased lipid within the cytoplasm of cells. "Analysis of the immunohistochemical results revealed that the expression of PTN was increased in some patients with steatosis." (PMID 28557334, 2017).
acute coronary syndrome (1 paper, 2023). Signs and symptoms related to acute ischemia of the myocardium secondary to coronary artery disease. "In the field of MI, the circulating concentration of pleiotrophin was independently associated with acute coronary syndrome and has also been implicated in cardiomyocyte apoptosis, yet few studies have evaluated its efficacy in terms of angiogenesis modulation after coronary occlusion." (PMID 37958681, 2023).
anaplastic ependymoma (1 paper, 2024). Anaplastic ependymoma is a rare, malignant type of ependymoma that most often arises in the supratentorial region of the brain of children and young adults and that manifests with variable symptoms including headaches, nausea, vision impairment, memory loss and difficulty walking. "In addition, cell communication analysis showed that the NRG3-ERBB4 pair is a key Ligand-receptor pair for anaplastic ependymoma, while in H3K27M-mutant diffuse midline glioma it is the PTN-PTPRZ1 pair that establishes contact with other cells." (PMID 38383423, 2024).
astrocytic tumor (1 paper, 2013). A glial tumor of the brain or spinal cord showing astrocytic differentiation. "Thus, our findings indicate that GalNAc4S-6ST mRNA expressed by astrocytic tumor cells is associated with poor patient prognosis likely by enhancing CS-E-mediated tumor cell motility in the presence of PTN and/or MK." (PMID 23349846, 2013). "We also found that PTPζ as well as PTN and MK were frequently expressed in astrocytic tumor cells." (PMID 23349846, 2013).
Autoimmunity (1 paper, 2023). The occurrence of an immune reaction against the organism's own cells or tissues. "This highlights the potentially important role of iAPCs in angiogenesis, tumors, infections, and autoimmunity through the differential production of MK and PTN upon TLR triggering." (PMID 37850119, 2023).
Azoospermia (1 paper, 2024). Absence of any measurable level of sperm,whereby spermatozoa cannot be observed even after centrifugation of the semen pellet. "In addition, we found downregulation of PTN and SDC2 as well as altered localization in non-obstructive azoospermia (NOA) patients, suggesting that downregulation of PTN and SDC2 may be associated with impaired spermatogenesis." (PMID 39285301, 2024).
cardiomyopathies (1 paper, 2025). "The synergistic actions of PTN and NCL mutually reinforce their effects, collectively exerting a significant impact on the initiation and progression of cardiomyopathies." (PMID 40717095, 2025). "The identification of PTN-NCL protein receptor pairs between C6 S100A4+ SMCs and ECs also provides a possible potential target for therapeutic intervention in cardiomyopathy." (PMID 40717095, 2025).